MIR6724-4 (microRNA 6724-4)
Synonyms: hsa-mir-6724-4
Gene: MicroRNA gene on chromosome 21 (8,432,530 to 8,432,621, forward strand). Ensembl gene ENSG00000275692.
Homologues: Paralogues in human: MIR6724-1 (100% identical), MIR6724-2 (100% identical), MIR6724-3 (100% identical).